CDKN2A (cyclin dependent kinase inhibitor 2A)
Diseases named in the same sentence as CDKN2A in open-access papers (continued):
Sharing a sentence is not in itself a finding about the gene and the disease.
cancer (continued). "It has been shown that deletion of MTAP in cancer cells is common due to its proximity to CDKN2A, a commonly deleted gene in cancer." (PMID 35744905, 2022). "CDKN2A has also demonstrated drug relevance in cancer treatment response portals in previous studies." (PMID 36588699, 2022). "As for fusion-positive EVs, miRNA implicated in cancer, inflammation, connective tissue diseases, and angiogenesis have found to be increased (MDM2, CDKN1A, CDKN2A, IGF1R, SOX2, YBX1, BRINP3)." (PMID 35454972, 2022). "Genetic and epigenetic alterations inactivating CDKN2A are encountered in many cancers, including pancreatic cancer." (PMID 35013462, 2022). "In the second dataset, LUSC, PIK3CA (46.5%), EGFR (7%), PDE4DIP (6.6%), KRAS (4.4%), and RELN (4.4%) were labeled with copy number gain, while CDKN2A (27.9%), LRP1B (17.4%), PTEN (9.8%), and PTPRD (9%) appeared to be the cancer genes with copy number loss." (PMID 35330454, 2022). "In drug sensitivity analysis, the expression of CDKN2A, DLAT, PDHA1, and GLS was negatively associated with some or most drugs in the Cancer Therapy Response Portal database, and the expression of DLST positively correlated." (PMID 36588699, 2022). "Numerous studies have proved that tumorigenesis of various cancers was correlated with the hypermethylation of CDKN2A." (PMID 36209249, 2022). "It is reasonable to believe that ARF-based therapies can provide synergistic effects with CDK4/6 inhibitors, especially in CDKN2A-deficient cancers." (PMID 35155432, 2022). "Studies have found that the copy number of CDKN2A/p16 was deleted in many cancers, including oral squamous cell carcinoma (OSCC), head-neck squamous cell carcinoma (HSCC) and ESCC." (PMID 35396552, 2022). "It is well known that genetic CDKN2A inactivation contributes to malignant transformation, cancer metastasis, and therapeutic sensitivity of cancers to drugs, including CDK4/6 inhibitors and their combination with PD-1 blockade." (PMID 36531022, 2022). "Studies have shown that the mutation or defect of CDKN2A in cancer cells can induce EMT, so as to promote the invasion and metastasis of cancer cells." (PMID 35311137, 2022). "Using sequencing datasets from 1,970 melanomas, we found that cancers with RB1 pathway mutations, including CDKN2A/p16, have significant co-occurrence of mutations in TERT and TPTE." (PMID 34983823, 2022). "CDKN2A is a common inactivated gene across cancer types, and it inhibits cancer cell proliferation by targeting the cell cycle." (PMID 36003780, 2022). "In 25 analyses of 17 cancer types, we have identified 19 to 169 significant genes by copy deletion, including RB1, PTEN and CDKN2A as the most significantly deleted genes among all cancer types." (PMID 36726722, 2022). "Consistent with its role in cancer, Cdkn2a knockout mice reveal a systemic phenotype affecting a variety of tissues and cellular processes." (PMID 34605899, 2022). "In certain C2 subtype cancers, p16INK4A expression was markedly downregulated together with homozygous CDKN2A deletion." (PMID 36077637, 2022). "To characterize the true genomic coordinates of CDKN2A deletion fragments in cancers, we extracted base-resolution sequence information of interstitial CDKN2A deletions from available published articles and our sequencing data." (PMID 36531022, 2022).
cancer (continued). "PV were detected in 13 cancer predisposition genes including ATM (n=4), BLM (n=1), BRCA1 (n=1), BRCA2 (n=7), BRIP1 (n=1), CDKN2A (n=1), CHEK2 (n=9), FANCC (n=1), MUTYH (n=10), NBN (n=1), PALB2 (n=1), RAD51D (n=1) and STK11 (n=1)." (PMID 36091166, 2022). "Serum cancer antigens CA125 and CA19-9 were positively associated with SMAD4 alterations while high CEA was enriched in wild-type CDKN2A subgroup." (PMID 35180847, 2022). "Frequent copy‐number aberrations were also found for important cancer genes, such as CDKN2A, KIT, MDM2, CCND1, CDK4, and PAK1, among others." (PMID 35229492, 2022). "The most frequent cancer genes involved in susceptibility of PDAC include BRCA1 and BRCA2, CDKN2A, STK11 and MMR genes." (PMID 35625944, 2022). "It has been previously reported that homozygous deletion of approximately 170 kilobase pairs (kb), including the CDKN2A locus, can be detected in human cancers by MSI analyses." (PMID 36531022, 2022). "We found a 5.1 kb CDR (chr9: 21,970,277 - 21,975,386, hg19) that spanned from the P16INK4A promoter to intron-2 in 83 (90%) of 92 reported cancer cell lines or tissue samples containing interstitial CDKN2A deletions (blue lines)." (PMID 36531022, 2022). "We evaluated the clinicopathological correlates of the 7 SMGs, together with 6 additional cancer genes identified from at least 2 previous HCC genomics studies and mutated in ≥3 HCCs of the current cohort (APOB, ARID2, CDKN2A, KEAP1, RB1 and TSC2)." (PMID 35508466, 2022). "The three genes (GCSH, LIPT1, CDKN2A) that we used to construct cuproptosis-related prognostic models played important roles in the progression of various types of cancer." (PMID 36195876, 2022). "Here, we reported that approximately 87% of genetic P16INK4A inactivation by CDKN2A SCND is accompanied by P14ARF inactivation in human cancer cell lines or tissues." (PMID 36531022, 2022). "A pan‐cancer study of chromosome arm‐level CNV found that deletions on the 9p arm, which contains the CDKN2A/B genes, were among the most substantial arm‐level events in 33 cancer types." (PMID 35253368, 2022). "In particular, the methylation status of CDKN2A and RASS1FA has been long implicated in the progression of cancer and the inactivation of p16 and p14 tumor suppressor genes." (PMID 35186184, 2022). "From the remaining two thirds of cases, an aberrant splicing involving the D153 residue appears in 5.16% of all CDKN2A affected cancer patients." (PMID 35158934, 2022). "In line with this, experiments in mice showed that an increased gene dosage of the Cdkn2a locus provides the animals with resistance to cancer while maintaining the same life span." (PMID 33078209, 2021).
cancer (continued). "In this model, expression of HRASG12V and Cdk4, which reflect Ras-MAP kinase activation as well as inactivation of the CDKN2A-mediated G1 restraints characteristic of cSCC, are sufficient to drive cancer progression by normal diploid epidermal keratinocytes." (PMID 34584216, 2021). "We further extended our analysis on other members of RB1 pathway, including CDKN2A (p16Ink4a), CCND1, CDK4, and CDK6, which are often mutated in different cancers." (PMID 33591981, 2021). "FadA is a crucial pathogenic factor of F. nucleatum and changes methylation of the cyclin-dependent kinase inhibitor 2A (CDKN2A) promoter and infiltration of macrophage in cancer tissues." (PMID 33663382, 2021). "In a rat model of HCC, combination therapy with a CDKN2A inhibitor and transarterial chemoembilization promoted cancer cell necrosis." (PMID 34497633, 2021). "In contrast, the repression of Cdkn1a, Cdkn2a, Adam10, Pten and muscle-specific genes in different cancer cell lines or myoblasts cells depends on recruitment of HDAC1, hence, deacetylation of lysine residues in N-terminal tails of histones." (PMID 33731112, 2021). "A number of other genes implicated in cancer pathogenesis have also been observed to be recurrently mutated in human cSCC, such as NOTCH1, CDKN2A, KNSTRN, and HRAS." (PMID 34584216, 2021). "Here, we reviewed CDKN2A germline alterations reported among individuals and families with cancer in the literature, specifically addressing the cancer phenotypes in relation to the molecular consequence on p16INK4A and p14ARF." (PMID 33766116, 2021). "Tumor suppressor genes located at CDKN2A/B locus (p15INK4b, p16INK4a, and p14ARF) are most regularly silenced or deleted in cancers relating to humans." (PMID 33896386, 2021). "CDKN2A was highly expressed in cancer tissues and significantly impacted the prognosis of diverse cancers." (PMID 34405225, 2021). "A significant positive correlation was observed between gene expression of CD274 (PD-L1) and CDKN2A/MTAP in a subset of TCGA cancers, which indicates decreased PD-L1 expression in cancers with 9p21 loss." (PMID 34556668, 2021). "CDKN2A inactivation also inhibited apoptosis and promoted proliferation/migration/invasion of cancer cells." (PMID 35004325, 2021). "The genomic loci of type I interferon gene cluster, located ~320 kb upstream of MTAP on 9p21, is often co-deleted with CDKN2A/MTAP in a subset of cancers." (PMID 34556668, 2021). "Our RNA-seq analysis validated the known mutations in cancer-related genes, GATA3 and CDKN2A, that have been reported for the three commercial CLs." (PMID 35011679, 2021). "Several genetic and epigenetic aberrations of CDKN2A lead to enhanced tumorigenesis and metastasis with recurrence of cancer and poor prognosis." (PMID 33778063, 2021).
cancer (continued). "Except for genes that had been shown to be mis-regulated in many cancer types, such as CDKN2A, CCND1, and IL6, we also detected a cohort of genes that had been newly or rarely reported in LC." (PMID 33628593, 2021). "Taken together, these results suggest therapeutic agents that target CDKN2A and RPTORin cancers that share these defective genes." (PMID 33909629, 2021). "The expression of tumor suppressor genes, such as Cdkn2a and Notch1, was downregulated in stem-like cancer cells compared to control stem-like cells." (PMID 34785704, 2021). "9p21.3 was the most significantly deleted segment in AK and harbors 10 cancer genes, including CDKN2A, JAK2, and MLLT3." (PMID 33482222, 2021). "The CDKN2A locus encodes two tumor suppressors, p16INK4a (INK4a) and p14ARF (ARF), and is among the most frequently mutated in human cancers." (PMID 34439790, 2021). "The tumor suppressor gene p16INK4a/CDKN2A, which is functionally linked with cell-cycle regulation and senescence, has also been shown to regulate plasticity and cancer through chromatin remodeling." (PMID 33430239, 2021). "In NSCLC, like in other cancers, patients with only CDKN2A gene HD have a longer survival compared to patients with IFN I and CDKN2A genes HD." (PMID 34249754, 2021). "Our data displayed a number of promising expressions of CDKN2A in cancer tissues that were strikingly inferior than that of the non-tumorous (P = 0.004)." (PMID 33896386, 2021). "ANRIL, an anti-sense RNAs co-clustered with the p15/CDKN2B-p16/CDKN2A-p14/ARF locus in chromosome 9p21, is involved in cancers and cardiovascular diseases." (PMID 34044272, 2021). "Genetic inactivation of CDKN2A by SCND is very frequent in many human cancers, which is also associated with metastasis of cancers." (PMID 35004325, 2021). "Despite being an anti-cancer target, MTAP is genomically deleted in 15% of human cancers together with the neighboring CDKN2A, one of the most frequently deleted tumor suppressor genes in human cancers." (PMID 33893330, 2021). "MCC and CDKN2A methylation co-occurred in 57% (16/28) of the carcinomas positive for either marker in the colon but only 25% (2/8) in the rectum/rectosigmoid region." (PMID 34298744, 2021). "Most significantly CDKN2A loss and RB1 loss are mutually exclusive in most cancers that lose these genes at a significant level (>5%), suggesting that the control of CDK4/6 activity and RB-status appear to define a single element of the pathway." (PMID 32242058, 2020). "The MTAP gene encodes 5-methylthioadenosine phosphorylase, which is associated with the purine and methionine salvage pathways, located in the region adjacent to the CDKN2A gene and frequently codeleted in cancers." (PMID 32887687, 2020). "PCR analysis confirmed the loss of Cdkn2a; PCR also revealed that Cdkn2a−/−-RT2-cancer cells expressed Tag." (PMID 32165639, 2020). "Genetic and epigenetic alterations in the CDKN2A gene resulting in expression changes have been observed in many types of cancer." (PMID 32486347, 2020). "CDKN2A is the second most frequently inactivated tumour suppressor gene in cancer 9, 11 and its inactivation is achieved in the majority of cases via homozygous deletion or promoter hypermethylation." (PMID 31916407, 2020).
cancer (continued). "Similar findings were reported by in a further study which found only 44% of serum samples from cancer patients exhibited hypermethylation of the CDKN2A gene promoter." (PMID 33135722, 2020). "The tumor suppressor gene P16 (cyclin-dependent kinase inhibitor 2A) is a well-known target that suffers DNA methylation silencing in human cancers." (PMID 32703154, 2020). "DeClust identified poor prognosis subtypes in KIRC, KIRP, and LUAD, which were enriched for CDKN2A deletions, highlighting that for these cancer types, cancer cell-intrinsic molecular programs are key drivers of prognosis." (PMID 32111252, 2020). "While the parental RT2-cancer cells were susceptible to CIS and to apoptosis, the Cdkn2a-loss mutant cell lines were resistant to CIS but susceptible to apoptosis in vitro." (PMID 32165639, 2020). "p16INK4a (CDKN2A) is a critical component of the CDK4/6 complex, and its high protein expression in cancer cells often indicates Rb loss of function." (PMID 32626773, 2020). "Tumor suppressor genes in the CDKN2A/B locus (p15INK4b, p16INK4a, and p14ARF) function as biological barriers to transformation and are the most frequently silenced or deleted genes in human cancers." (PMID 32183138, 2020). "Together the data prove that Stat1 is needed to activate p16Ink4a in vitro and in vivo and that Stat1-mediated activation of Cdkn2a is needed to induce senescence in cancer cells." (PMID 32165639, 2020). "The interferon alpha gene alterations observed are likely because they cluster near band 9q21 that is proximal to the locus of CDKN2A, which was included in the screened gene set and is commonly deleted in both cancer sets." (PMID 32033319, 2020). "Several studies have reported that CDKN2A codeleted genes are involved in the hidden molecular features of cancers." (PMID 32887687, 2020). "In this study, we mined and integrated the cancer genomics and chemogenomics data to investigate the roles of CDKN2A genetic alterations in PDAC patients’ prognosis and treatment." (PMID 33322698, 2020). "p16INK4a, encoded by the CDKN2A gene (p16 hereafter), represents an important link between cancer, cellular responses to stress, and aging." (PMID 32483135, 2020). "The tumor suppressor gene, CDKN2A, is frequently silenced by epigenetic mechanisms in many cancers; in the case of MPM it is mostly silenced via genomic deletion." (PMID 33304846, 2020). "Known cancer genes such as EGFR, EZH2, or CCDN2 were frequently affected by duplications and other known cancer genes such as CDKN2A, RB1, KLK2, or CD79A were frequently affected by deletions." (PMID 32604718, 2020). "In contrast, 80% of the RT2.CRISPR-Cdkn2a-cancer cells grew in syngeneic mice, demonstrating that natural immune responses required the senescence-inducing Cdkn2a gene to control these highly immunogenic cancer cells." (PMID 32165639, 2020). "Among the INK4 proteins, loss of p16INK4a (encoded by the CDKN2A gene, also called INK4a) occurs most frequently in human cancers." (PMID 32344731, 2020).